HOTAIR (HOX transcript antisense RNA)
Diseases named in the same sentence as HOTAIR in open-access papers (continued):
Sharing a sentence is not in itself a finding about the gene and the disease.
tumor (continued). "Among them, HOXC11, HOXC10, HOXC8, and HOXC12 interact with HOTAIR in gastrointestinal tumors to jointly promote tumor formation and development." (PMID 36924407, 2023). "The tumor suppressor miR-34a, which binds to the HOTAIR mRNA sequence, participates in the anti-metastatic mechanism of genistein." (PMID 36770654, 2023). "Recently, the upregulation of HOTAIR in HCC was observed in several studies, and its expression in patients was associated with clinicopathological features such as metastasis and tumor size, and correlated with poor prognosis." (PMID 37240232, 2023). "Many in vivo and in vitro studies showed the upregulation of HOTAIR expression with enhanced tumor invasion and metastasis." (PMID 36980864, 2023). "Several studies have shown that HOTAIR inhibition leads to G0/G1 cell cycle arrest, thereby inhibiting tumor cell proliferation." (PMID 36924407, 2023). "Numerous meta-analyses have focused on the expression of HOTAIR and its value in tumor prognosis and diagnosis, such as digestive system carcinomas, hepatocellular carcinoma, colorectal cancer (CRC), and head and neck tumors." (PMID 36924407, 2023). "Recent studies have reported that HOTAIR expression is upregulated in BC cells and tumor tissues, with its expression levels correlated with cell proliferation and metastasis." (PMID 36997931, 2023). "In esophageal cancer, HOTAIR sponges miR-148a causing a positive modulation of the expression of the EMT-TF Snail2 therefore promoting EMT, invasion and, lastly, metastasis of tumor cells." (PMID 37308974, 2023). "In particular, the aberrant expression of HOTAIR plays an important role in BC by contributing to tumor progression." (PMID 37175800, 2023). "For example, some preclinical studies have begun to focus on the potential of targeting certain specific lncRNAs to complete tumor therapy and related drug development, such as H19, HOTAIR, LUNAR1, etc.." (PMID 36837389, 2023). "This signature consists of 5 genes (HOTAIR, PLK1, LAMA3, EDA2R, and IKZF3) that are closely linked to tumor development." (PMID 37904416, 2023). "This study observed that AQB enhances the expression of tumor suppressors by interfering with the recruitment of PRC2 via the disruption to the interaction of HOTAIR with EZH2." (PMID 36997931, 2023). "Operating as a miRNA sponge, increased levels of HOTAIR can, on one hand, favor tumor growth and proliferation and on the other hand, contribute to drug resistance by sponging miR-125." (PMID 38004481, 2023). "LncRNAs, including ANRIL, HOTAIR, MALAT1, SAMMSON, etc., have been implicated to play an essential part in tumor progression, metastasis, and anti-tumor immunity in melanoma via numerous research." (PMID 37770477, 2023). "HOTAIR, an oncogenic long non-coding RNA (lncRNA), and miR-130a, a tumor suppressor miRNA, play crucial roles in tumor progression." (PMID 38114755, 2023). "Clinical studies have shown that the aberrant HOTAIR expression is closely related to tumor metastasis, recurrence and poor prognosis in breast cancer, colon cancer, liver cancer and other tumor tissues." (PMID 36810034, 2023). "Antisense oligonucleotides of MALAT1 and HOTAIR have shown effective tumor‐inhibiting power in preclinical models." (PMID 36992525, 2023). "Metastasis of squamous cell carcinoma is also supported by the upregulation of HOTAIR, which induces tumor invasion and stimulates EMT." (PMID 36770654, 2023). "HOTAIR has been reported to be an upstream regulator of MALAT1, and promising results have been obtained from the use of MALAT1 and HOTAIR in regulating oncogenic immune-modulatory proteins CD80 and MSLN in tumor-associated macrophages (TAMs)." (PMID 36997931, 2023). "Sun reported that STAT3/lncRNA HOTAIR interacts with pEZH2-Ser21 to regulate the growth of head and neck squamous cell carcinoma, thereby improving the anti-tumor efficacy of cisplatin and cetuximab therapy." (PMID 36672374, 2023).
tumor (continued). "New research suggests that HOTAIR is a chromatin regulation system that routinely controls tumor metabolism, proliferation, etc.." (PMID 36816362, 2023). "In NSCLC, tumor samples and cell lines expressed higher HOTAIR levels as compared to normal counterparts." (PMID 37370745, 2023). "For example, overexpression of lncRNA HOTAIR in HCC cell lines promoted CCL2 secretion, which is necessary for tumor-associated macrophages and recruitment of myeloid-derived suppressor cells." (PMID 36035299, 2022). "Since the discovery of HOTAIR, multiple studies have elucidated its critical role in tumor growth, apoptosis, invasion, metastasis, tumor stem cell differentiation, and drug resistance." (PMID 36233075, 2022). "In univariable Cox regression analyses, only HOTAIR positivity (P = 0.009) and depth of tumor invasion (T) (P = 0.02) affected the overall survival of patients statistically significant." (PMID 35347094, 2022). "Western blot analysis indicated that Suv39H1 levels significantly decreased in tumor tissues of the HOTAIR silencing group (p < 0.05)." (PMID 35619625, 2022). "Consistent with the results in vitro, HOTAIR knockdown along with oxaliplatin treatment decreased the tumor weight and volume compared with that in the control group treated with oxaliplatin only." (PMID 35798695, 2022). "Plasma lncRNA HOTAIR has been shown to promote the development of tumor and influence the poor prognosis of tumor." (PMID 36741380, 2022). "In mouse models of CRC, HOTAIR knockdown markedly inhibited the tumor growth when treated with oxaliplatin." (PMID 35798695, 2022). "Here, we show that depletion of HOTAIR and NF-κB subunit p65 impairs the self-renewal of BCSCs and their tumor-initiating capacity, suggesting that HOTAIR-mediated NF-κB signaling is critical for maintaining BCSC self-renewal and tumorigenicity." (PMID 36273585, 2022). "HOTAIR is the first lncRNA found to have reverse transcription effect, which plays a role in many diseases, such as tumor, rheumatoid arthritis, heart disease and so on." (PMID 35093153, 2022). "LncRNAs GHSROS, HNF1A-AS1, and HOTAIR showed high expression in tumor tissue and exosome content in NSCLC, and a panel that consisted of all five lncRNAs improved diagnosis of NSCLC." (PMID 36553216, 2022). "Mechanistically, HOTAIR was involved in tumor progression by sponging diverse miRNAs such as miR-143-3p, miR-148a, miR-20a-5p, miR-206, miR-23b, and miR-214/miR-217." (PMID 35656022, 2022). "Generally, HOTAIR as a ceRNA modulates miRNA expression and affects the actions of miRNA on target genes, thus modifying tumor progression." (PMID 35248107, 2022). "Overall, HOTAIR is thought as an important epigenetic regulator that vigorously participates in carcinogenesis, tumor growth, progression, and metastasis of PTC." (PMID 36494673, 2022). "According to literature reports, we can see that the current research on the role of HOTAIR in tumor chemotherapy resistance is still in its infancy." (PMID 36100611, 2022). "Overexpression of the lncRNA HOTAIR is significantly correlated with tumor progression and poor prognosis in many kinds of tumors and is a powerful predictor of tumor metastasis." (PMID 36579891, 2022). "In this study, we measured HOTAIR expression in OS samples and their corresponding non-tumor tissues." (PMID 35435107, 2022). "On the other hand, consistent with the oncogenic function of HOTAIR, we observed a significantly higher expression of HOTAIR in GC tissues as compared to adjacent non-tumor tissues." (PMID 35186192, 2022). "In GBM, HOTAIR knockdown suppressed tumor growth, migration, and invasion and EMT, whereas exosomal HOTAIR accelerated TMZ resistance by the miR-519a-3p/RRM1 pathway." (PMID 36100611, 2022). "It was found that HOTAIR had an influence on PCDH10 renowned as a tumor suppressor gene, which suffered a methylated alteration resulted by HOTAIR through interacting with miR-148 and DNMT1, bringing about oncogenic changes in GC." (PMID 35810299, 2022).
tumor (continued). "HOTAIR upregulation was identified in an ovarian cancer cell model, and it was found to increase tumor progression and promote tumor aggressiveness and metastasis via activation of the PI3K/AKT/mTOR pathway." (PMID 35813070, 2022). "HOTAIR is highly-expressed in the tumor tissues of RB, which serves as a predictor of poor prognosis in patients with RB, implying a possible role of HOTAIR in the initiation and development of RB." (PMID 35248107, 2022). "In vivo data also showed that stable silencing of HOTAIR repressed tumor growth and increased the sensitivity of radiotherapy." (PMID 36438563, 2022). "In breast cancer, HOTAIR is able to suppress the tumor inhibitor miR-7, by upregulating the expression levels of c-Myc, TWIST and miR-9 and maintaining the BCSC pool." (PMID 39086963, 2022). "Subcutaneous tumor formation model in nude mice demonstrated that HOTAIR knockdown inhibited the tumor growth and metastasis of BC in vivo." (PMID 35619625, 2022). "Based on the confirmation that HOTAIR deletion inhibited the proliferation and migration of OS cells in vitro, it was further revealed that HOTAIR knockdown inhibited tumor growth in vivo." (PMID 35435107, 2022). "The aim of this study is to investigate the interlinkage between MALAT1 and HOTAIR and their regulatory activity on immunomodulation by examining the expression profile of CD80 and MSLN in tumor-associated macrophages in the hormonal, HER2+, and TNBC subtypes." (PMID 36387279, 2022). "The results showed HOTAIR depletion resulted in a much weaker tumor presence compared with control cells as assessed by a limiting dilution xenograft analysis, suggesting that HOTAIR knockdown reduced tumor-initiating capacity." (PMID 36273585, 2022). "Consistent with the results obtained by in vitro assay, the tumor growth rate was decreased notably after silencing HOTAIR in vivo." (PMID 35248107, 2022). "By studying the regulation of HOTAIR on miRNA, we can conclude that HOTAIR can be used as a new target for tumor therapy and provide new ideas for tumor therapy." (PMID 35093153, 2022). "The silencing of HOTAIR by siRNAs inhibits tumour cell invasiveness in breast cancer and reduces tumour growth in pancreatic cancer." (PMID 35052495, 2022). "Meanwhile, HOTAIR is positively correlated with tumor cell proliferation, survival, invasion and resistance to treatment via molecules such as chromatin modifiers and ubiquitin ligases." (PMID 35042456, 2022). "Expression of ProT and HOTAIR was significantly higher in tumor tissues than their normal tissue counterparts." (PMID 36471329, 2022). "The expressions of HOTAIR and Suv39H1 in BC cell lines and 20 pairs of BC and matched tumor-adjacent normal tissues were measured using qRT-PCR to verify the clinical significance of LncRNA HOTAIR and Suv39H1 in BC." (PMID 35619625, 2022). "Previous studies have been found that the expression of HOTAIR is significantly higher in cancer tissues than in matched tumor-adjacent healthy tissues." (PMID 35042456, 2022). "HOTAIR is a kind of lncRNA with trans- transcriptional regulation, which can negatively regulate chromosome transcription, reorganize chromatin and promote tumor progression." (PMID 35963868, 2022). "In line with the data obtained from clinical tumor samples, there was also a positive correlation between the expression levels of ProT and HOTAIR in urothelial cancer cell lines (r = 0.7661, p = 0.0266)." (PMID 36471329, 2022). "Accordingly, HOTAIR has been extensively studied in various types of tumors, and results have shown that it is widely involved in tumor cell proliferation, apoptosis, angiogenesis, invasion, and metastasis." (PMID 35813070, 2022). "For example, the expression of HOTAIR is closely related to the neoplasm staging and poor prognosis of glioma." (PMID 34722321, 2021).
tumor (continued). "We observed that siHOTAIR had no obvious influence on tumor growth alone; however, combined with imatinib, downregulating HOTAIR remarkably inhibited tumor growth, indicating that knocking down HOTAIR enhanced the efficacy of imatinib." (PMID 33824300, 2021). "HOTAIR has been detected in the blood of BC patients, and its circulating DNA level significantly correlated with the clinical stage of the tumor." (PMID 34576322, 2021). "In this review, we briefly summarize the impact of lncRNA HOTAIR expression and functions on different human solid tumors, and emphasize the potential of HOTAIR on tumor prognosis and therapy." (PMID 34367966, 2021). "In BC, HOTAIR is able to interact with different miRNAs promoting tumor progression, such as miR-7, miR-206 and miR34a." (PMID 34576322, 2021). "The tumor suppressor miR-34a is also upregulated by genistein, directly targeted HOTAIR, modulating cell proliferation, migration, and invasion, in both PC3 and DU145 PCa cells." (PMID 33540611, 2021). "Knockdown of HOTAIR increased the permeability of the blood–tumor barrier (BTB) by connecting with miR-148b-3p as a target RNA." (PMID 33980320, 2021). "Bioinformatics analysis and previous studies have identified that HOTAIR can interact with miR-203, which has been considered a tumor suppressive miRNA." (PMID 34539782, 2021). "In-vivo therapeutic applications: In vivo, knockdown of HOTAIR using shRNA inhibited tumor growth and invasiveness and enhanced chemosensitivity." (PMID 34322395, 2021). "HOTAIR also activated the mTOR pathway via regulating miR-125a, resulting in increased tumor viability." (PMID 34322395, 2021). "Invasion and metastasis: HOTAIR downregulation inhibited tumor invasiveness and migratory abilities." (PMID 34322395, 2021). "For instance, the elevation of HOTAIR expression in ER+ BC cells, regulated by estradiol (E2), leads to tumor formation." (PMID 34885213, 2021). "In human RCC tissues, HOTAIR expression is over-expressed, and HOTAIR over-expression in tumor tissues is correlated with tumor progression and poor patient prognosis." (PMID 33593347, 2021). "In both murine and human tumour cells, HOTAIR‐sbid impaired the ability of HOTAIR to bind Snail and, in turn, trigger H3K27me3/EZH2‐mediated repression of Snail epithelial target genes." (PMID 34296520, 2021). "Higher expression of HOTAIR was related to tumor size, distant metastasis, and tumor differentiation." (PMID 33954114, 2021). "We evaluated lentivirus-mediated HOTAIR overexpression and anti-HOTAIR AQB treatment alone or combination in TBD orthotopic tumor model established in Bagg albino (BALB)/c nude mice." (PMID 34887871, 2021). "In triple-negative breast cancer (TNBC) patients, high HOTAIR expression in tumor tissues is strongly correlated with lymph node metastasis, and it is directly associated with the androgen receptor (AR)." (PMID 33540611, 2021). "For example, lncRNA HOTAIR is positively correlated with metastasis of BC; HOTAIR acts as a sponge for miR-20a-5p and significantly influences the migration and invasion of tumor cells via the HOTAIR/miR-20a-5p/HMGA2 pathway." (PMID 34079084, 2021). "Of particular note, HOTAIR, which is well characterized in many primary tumours, was included in our 10-lncRNA signature." (PMID 33621953, 2021). "HOTAIR is highly expressed in OS tumor samples and cells and its upregulation was closely correlated with advanced tumor stage along with highly histological grade." (PMID 34576322, 2021). "We also evaluated the role of lncRNA HOTAIR, a regulator of posterior HOX genes expression, recently associated with GEP-NEN tumor progression." (PMID 34208964, 2021). "HOTAIR appears to be a powerful predictor of BC tumor progression: its upregulation has been described in primary BC tumors with high metastatic potential and poor survival." (PMID 34576322, 2021).
tumor (continued). "The crucial prognostic role of HOTAIR in this tumor type is well documented and in addition to being aberrantly expressed it is also directly related to the clinical-pathological characteristics and poor survival of patients." (PMID 33540611, 2021). "Subsequently, the relative expression of HOTAIR and miR-130a was analyzed in four groups’ tumor samples using qRT-PCR, which demonstrated the successful intervention of HOTAIR expression by siHOTAIR in vivo." (PMID 33824300, 2021). "In CC, enhanced HOTAIR expression can lead to progressive tumor stages, lymphatic node and lymphatic vessel metastasis, adenocarcinoma, and poor prognosis." (PMID 34885213, 2021). "As expected, we found that HOTAIR was significantly upregulated in CC cells lines and CC biopsies samples compared to the non-tumor cell line HaCat and normal tissues samples patients, respectively." (PMID 34778043, 2021). "In AML blasts, HOTAIR affects the expression of endogenous miR-193a target, a tumor suppressor gene in AML, able to represses c-kit expression." (PMID 33540611, 2021). "In liver cancer, HOTAIR upregulation correlates with clinical-pathological features and tumor progression and its silencing increases chemotherapy sensitivity." (PMID 34576322, 2021). "Aberrant HOTAIR expression has been described in lymphocytes surrounding the metastatic tumor cells of metastatic melanoma patients." (PMID 33540611, 2021). "In these tumor types, high levels of HOTAIR are correlated with a high probability of metastatic progression." (PMID 34576322, 2021). "High expression of HOTAIR was closely related to progressive disease, worse survival, and more potential in tumor recurrence after radical operation." (PMID 33892664, 2021). "HOTAIR is known to expedite tumor initiation and assist in tumor progression in many different cancers." (PMID 33498666, 2021). "In conclusion, our results provide convincing evidence that lncRNA HOTAIR drives aberrant gene transcription and immune escape from tumor cells through the NF-κB pathway." (PMID 34887871, 2021). "Among them, lncRNA HOTAIR as an oncogene has been confirmed by numerous studies and plays a key role in tumour development." (PMID 34180119, 2021). "Mechanically, HOTAIR played an oncogene function to accelerate tumor progression mainly through epigenetic regulation, EMT, miRNA-mediated downstream signaling pathways, and regulation of other signaling pathways such as the Wnt/β-catenin signaling pathway." (PMID 34367966, 2021). "In this review, we discuss the relation between lncRNA HOTAIR and different microRNAs, highlighting in particular the contribution of these functional interactions to tumor initiation and progression." (PMID 33540611, 2021). "Reducing HOTAIR expression induces inhibition of colony formation, G0/G1 cell cycle arrest, and inhibition of tumor growth in situ." (PMID 34722321, 2021). "For example, a recent study proposed an innovative RNA-based strategy to interfere with the oncogenic lncRNA HOTAIR in tumor cells, preventing HOTAIR/EZH2-mediated epithelial-to-mesenchymal transitions." (PMID 33669945, 2021). "In NSCLC tumor tissues and cell lines (A549, PC9, H1299, and H520), Besides, HOTAIR was associated with LSH (HELLS) to regulate the FOXA1 to FOXA2 ratio and promote cell migration and invasion." (PMID 32438606, 2020). "HOTAIR supports tumor-cell stemness, proliferation and metastasis, as well as therapeutic resistance in 26 human tumor types, by interacting with molecules such as miRNAs, ubiquitin ligases, and chromatin modifiers." (PMID 32928281, 2020). "Early studies highlighted the aberrant expression of HOTAIR in primary BC tumors with high metastatic potential and poor survival, suggesting HOTAIR as a powerful predictor of BC tumor progression." (PMID 32397382, 2020). "Another study on Chinese CRC cases showed significant over expression of HOTAIR in tumor compared with normal margins." (PMID 31956395, 2020).